CST3 (cystatin C)
Diseases named in the same sentence as CST3 in open-access papers (continued):
Sharing a sentence is not in itself a finding about the gene and the disease.
diabetes (269 papers, 2008 to 2026). "Subgroup analysis results showed that, in individuals with diabetes and aged ≥65 years, maintaining a low level of Cystatin C was associated with an increased risk of cognitive decline compared with maintaining a medium level." (PMID 41778039, 2026). "The associations between diabetes and declined eGFR calculated by cystatin C and creatinine were observed in this analysis." (PMID 41280371, 2025). "In this nationally representative study of Chinese adults aged 45 years and older, we found that the intraindividual difference between cystatin C- and creatinine-based eGFR was significantly associated with the prevalence of diabetes." (PMID 41280371, 2025). "The association between eGFRdiff and diabetes was also significant after adjusting for cystatin C-based eGFR (OR: 1.32, 95% CI: 1.16–1.50)." (PMID 41280371, 2025). "The associations between cystatin C and incident stroke remained in subgroups stratified by age, sex, obesity, residence, smoking, hypertension, and diabetes." (PMID 38681764, 2024). "In this meta-analysis of 15 studies with 3093,792 participants, modifiable risk factors associated with a higher risk of LVR after MI included hypertension, diabetes, myocardial infarction site, coronary artery lesions, cystatin C (CysC), BNP, as well as CKMB." (PMID 39560578, 2024). "A few studies have compared eGFR based on creatinine or cystatin C for the association with all‐cause mortality among individuals with diabetes." (PMID 37128173, 2023). "Multivariate Cox regression analysis indicated that eGFR (cystatin C), diabetes mellitus, and liver disease were independently associated with 3-year all-cause mortality." (PMID 37187794, 2023). "Compared with the 1st quartiles of creatinine and Cystatin C, the risk of diabetes mortality were higher in the highest quartiles (HR: 5.16, 95% CI: 1.87–14.22; HR: 10.06, 95% CI: 4.20-24.13)." (PMID 37775738, 2023). "Our study showed that eGFR (cystatin C), diabetes mellitus, and liver disease were independently associated with 3-year all-cause mortality in the TAVI cohort." (PMID 37187794, 2023). "Older age, lower preoperative eGFR, higher rGFR of the operative side, lower rGFR of the healthy side, higher serum cystatin C, diabetes, open surgical approach, and shorter TFS were associated with worse long-term eGFR." (PMID 37906264, 2023). "In the multivariate analysis, diabetes and cystatin C were significantly associated with the interhemispheric difference in the number of the lacuna (OR = 2.03, p = 0.038; OR = 5.73, p = 0.024) and CSVD score (OR = 2.22, p = 0.033; OR = 9.67, p = 0.008)." (PMID 37508948, 2023). "Despite using different eGFR cutoffs in the analyses, these findings are consistent with our results on the association between eGFR based on creatinine or cystatin C and all‐cause mortality among participants with diabetes." (PMID 37128173, 2023). "In non-diabetes, the minor alleles of rs141640975 and rs144360241 were associated with higher levels of eGFRcreatinine-cystatin C." (PMID 36926036, 2023). "A 10% increase in Cystatin-C levels was associated with 13% increased relative risk of diabetes at baseline (11% and 9% by years 4 and 8)." (PMID 36094936, 2022). "The aim of this manuscript is to study the association between Cystatin-C, diabetes, and mortality and test for possible sex or racial/ethnic background modifications in these relationships." (PMID 36094936, 2022). "Specifically, we: 1) examine associations between Cystatin-C levels and diabetes prevalence and mortality risk, and 2) explicitly test for race/ethnic background and sex modifications on Cystatin-C." (PMID 36094936, 2022). "Higher log Cystatin-C values were associated with increased odds of diabetes and mortality at each time point." (PMID 36094936, 2022).
diabetes (continued). "Second, we proved that several traditional risk factors, such as age, diabetes mellitus, white blood count, and cystatin C, were independent risk predictors of PSCI in patients with lacunar infarction." (PMID 36090853, 2022). "Plasma cystatin C, as a measure of kidney function, was significantly lower in the diabetic groups as compared with their respective control groups consistent with diabetes associated hyperfiltration." (PMID 35048962, 2022). "After multivariate analysis, age, diabetes mellitus, white blood count, cystatin C, and SAA were independent risk predictors of PSCI." (PMID 36090853, 2022). "Recent work, including a meta-analyses, show clear evidence for increased diabetes and mortality risk for those with elevated Cystatin-C." (PMID 36094936, 2022). "Cystatin c is mainly associated with several medical conditions, including metabolic syndrome, diabetes, physical activity, smoking, diet and drinking." (PMID 35566636, 2022). "Cystatin-C was associated with higher risk of diabetes and mortality at baseline and at each of the follow-up assessment periods." (PMID 36094936, 2022). "Multivariate logistic regression analysis revealed that serum Cystatin C level, presence of hypertension and diabetes, HCY, age, and male were the risk factors for coronary artery lesions." (PMID 33466214, 2021). "High levels of cystatin-C are associated with age, male, gender, black race, weight, height, cigarette smoking, and subclinical inflammation, central adiposity, diabetes, and metabolic syndrome." (PMID 31561432, 2019). "The significant associations are in several major phenotype groups: C reactive protein, lipid profile, diabetes, cystatin C, heart event risk, heart rate, and height." (PMID 30704471, 2019). "Previous evidence revealed the significant association between cystatin C and metabolic risk factors, such as dyslipidemia, diabetes, and hypertension." (PMID 31317040, 2019). "Of note, several studies have reported that hypertension, dyslipidemia, and diabetes were associated with cystatin C level, which were the components of metabolic syndrome (MetS) and cardiometabolic risk factors." (PMID 31317040, 2019). "Male sex, obesity, diabetes, and plasma levels of cystatin C, GDF‐15, and CRP‐hs were independently associated with higher IL‐18 levels." (PMID 31596518, 2019). "In the whole cohort, baseline uNGAL-levels were significantly associated with diabetes, lower eGFR, Cystatin C, proteinuria, age and female sex." (PMID 28128223, 2017). "Baseline uNGAL was associated with female sex, diabetes, age, lower eGFR, Cystatin C, urine osmolality and proteinuria." (PMID 28128223, 2017). "Higher cystatin C was associated with male sex, higher prevalence of previous cardiovascular disease and diabetes mellitus, greater body mass index (BMI), greater waist-to-hip ratio, higher systolic blood pressure, and lower diastolic blood pressure." (PMID 29016597, 2017). "A causal involvement of cystatin C in the etiology of MetS or diabetes seems unlikely since genetic elevation of plasma cystatin C was not significantly related to these diseases." (PMID 27218257, 2016). "Serum cystatin C (CysC) has recently been shown to be associated with the incidence of type 2 diabetes mellitus (T2DM) and progression to the pre-diabetic state." (PMID 26849560, 2016). "Our study is to the best of our knowledge the first to examine the effects of genetic elevated cystatin C (here the major C allele of rs13038305) on incident diabetes and MetS." (PMID 27218257, 2016). "In this study we aimed to replicate these results and also investigate if cystatin C was causally associated with MetS and diabetes." (PMID 27218257, 2016). "Compared to CKD defined by serum creatinine, CKD defined by serum cystatin C appears to better predict and risk stratify patients with diabetes for end stage renal disease." (PMID 26576434, 2015).
diabetes (continued). "A clinic based study from China has shown that elevated levels of cystatin C are associated with severity of DR and are an independent risk factor for DR along with diabetes duration and HbA1c levels." (PMID 26576434, 2015). "The results showed that the significant risk factors included cystatin C (P = 0.007, OR = 5.081), the presence of hypertension (P = 0.011, OR = 3.527), age (P<0.001, OR = 1.181), GA (P = 0.002, OR = 1.089) and diabetes duration (P = 0.008, OR = 1.074)." (PMID 23843968, 2013). "There were significant independent associations between GDF-15 levels and current smoking, diabetes mellitus, and biomarkers indicating renal dysfunction (cystatin C), cardiac dysfunction (NT-proBNP, troponin T) and also inflammatory activity (CRP)." (PMID 24312445, 2013). "SBP, serum albumin, CRP were significantly associated with microalbuminuria (p value for uric acid was 0.068) while additional risk factors including total cholesterol, ALT, cystatin C and diabetes were significantly associated with overt albuminuria." (PMID 23947772, 2013). "Among the list, smoking, statin use, diastolic blood pressure, and BMI associated positively and significantly with aortic diameter, whereas coexisting diabetes mellitus associated negatively with aortic diameter, as did cystatin C." (PMID 22844527, 2012). "This could be attributed to increased risk of hypertension, diabetes mellitus, myocardial infarction, heart failure, peripheral artery disease, and stroke with increasing levels of serum cystatin C." (PMID 40707908, 2025). "In a nationally representative sample of middle‐aged and older Chinese, we used validated eGFR prediction equations to examine the associations of three eGFR measures based on creatinine, cystatin C, or both biomarkers with all‐cause mortality according to diabetes status." (PMID 37128173, 2023). "Cystatin C may increase the risk of diabetes by participating in interrelated processes of inflammation." (PMID 37056689, 2023). "Notably, the associations between MCI risk and cystatin C or glucose homeostasis were only founded in diabetes patients." (PMID 37056689, 2023). "Interestingly, the effect of cystatin C in increasing the risk of MCI was found only in the diabetes subgroup, and the OR of cystatin C in the diabetes subgroup was higher compared to the overall population, with a OR of 3.27 (95% CI, 1.01, 10.84)." (PMID 37056689, 2023). "Furthermore, we found that previous histories with diabetes and cystatin C were associated with the heterogeneity of lacunar number and CSVD scores between hemispheres." (PMID 37508948, 2023). "Using data from the HRS, a longitudinal study representative of middle aged and older adults (>50-years) from diverse race/ethnic groups in the US, we examined the associations between Cystatin-C and glomerular filtration rate, diabetes prevalence, and mortality." (PMID 36094936, 2022). "We hypothesize that Cystatin-C increments will be associated with increased odds of diabetes as well as mortality." (PMID 36094936, 2022). "There are several possible pathways by which elevated Cystatin-C could increase the risk of diabetes, and mortality." (PMID 36094936, 2022). "Cystatin-C dysregulations could be used as a risk indicator for diabetes and as a warning sign for accelerated risk of mortality." (PMID 36094936, 2022). "Cystatin-C, in addition to other biomarkers, could be used to create a comprehensive diabetes risk profile." (PMID 36094936, 2022). "We also hypothesize that Blacks, Latinos, and men will have stronger (more risk) associations between Cystatin-C and outcomes given known variabilities in diabetes and renal function in these groups." (PMID 36094936, 2022). "A 10% increase in Cystatin-C, measured at visit 1, was associated with 13% increase in the odds ratios of diabetes (log Cystatin-C OR visit-1 = 3.69, p<0.001) at visit 1, 11% at visit 2 (OR visit-2 = 3.00, p<0.001), and 9% at visit 3 (OR visit-3 = 2.45, p<0.001)." (PMID 36094936, 2022).
diabetes (continued). "After further adjusting for the variables in model 2 plus BUN, creatinine, TG, HDL-c, LDL-c, Hs-CRP, hemoglobin, cystatin C, and HbA1c, diabetes status was a significant risk factor for subsequent cognitive decline (unstandardized β estimate = −0.50, 95%CI = −0.98 ~ −0.02, model 3)." (PMID 35936393, 2022). "Cystatin-C has been linked to increased prevalence of metabolic syndrome, higher body mass index (BMI), waist circumference, and inflammation, all of which have complex relationships with diabetes risk and mortality." (PMID 36094936, 2022). "Linear regression models were used to analyse the association between SEP and cystatin C as well as the impact of cardiovascular risk factors (i.e., body mass index, blood pressure, blood glucose, diabetes mellitus, blood lipids, C-reactive protein, smoking) on this association." (PMID 34588554, 2021). "This may be explained, at least partly, by the close association of cystatin C with insulin resistance, obesity and hypertension conditions, which are closely related to diabetes; these associations have been shown in several studies." (PMID 32306911, 2020). "Serum cystatin C might be a powerful diagnostic tool to screen for multivessel disease in patients with diabetes mellitus and normal renal function." (PMID 32306911, 2020). "Age, discharge cystatin C, CRRT on ICU, and diabetes were associated with cystatin C-based CKD." (PMID 30363702, 2018). "Covariates associated with 3-month cystatin C-eGFR were age, cystatin C at discharge, and diabetes." (PMID 30363702, 2018). "In addition, both cross-sectional and prospective studies have identified cystatin C to be associated with metabolic risk factors as well as the incidence of the metabolic syndrome (MetS) and diabetes." (PMID 27218257, 2016). "Incident hypertension and diabetes are also associated with elevated cystatin C levels." (PMID 24868463, 2014). "At baseline there were independent associations between GDF-15 and current smoking, diabetes mellitus, biomarkers of cardiac (high-sensitivity troponin-T, NT-proBNP) and renal dysfunction (cystatin-C) and inflammatory activity (C-reactive protein), and previous cardiovascular disease (CVD)." (PMID 24312445, 2013). "Binary logistic regression analysis showed that the significant risk factors were cystatin C (P = 0.007, OR = 5.081), the presence of hypertension (P = 0.011, OR = 3.527), age (P<0.001, OR = 1.181), GA (P = 0.002, OR = 1.089) and diabetes duration (P = 0.008, OR = 1.074)." (PMID 23843968, 2013). "However, it remains unclear whether the intraindividual difference between cystatin C- and creatinine-based estimated glomerular filtration rates (eGFRdiff) is associated with diabetes." (PMID 41280371, 2025). "Therefore, assessment of serum cystatin-c seems to be a better diagnostic test for screening patient when serum creatinine level is inconclusive, especially, in certain individuals with longer duration of diabetes and other comorbidity." (PMID 37002266, 2023). "Additionally, a substudy of the EXAMINE trial, involving 5380 patients with recent ACS and type 2 diabetes mellitus, showed that cystatin-C was significantly associated with the composite endpoint (nonfatal MI, nonfatal stroke, or CV death) and mortality in this particular category of patients." (PMID 36676179, 2023). "In addition to its current use for monitoring renal health, Cystatin-C could be used as a risk indicator for diabetes as well as an early predictor of potentially premature mortality." (PMID 36094936, 2022). "On the other hand, it should be considered that Cystatin-C levels may be influenced by different cardiovascular risk factors, such as obesity, diabetes mellitus, smoking habit, chronic inflammation and thyroid disease, whose prevalence increases in older people." (PMID 34661901, 2022).
diabetes (continued). "Because insulin resistance is an important element in the development of type 2 diabetes mellitus, these findings suggest that insulin resistance may play an additional role in the link between cystatin C and type 2 diabetes mellitus, although the underlying mechanism remains unclear." (PMID 32306911, 2020). "For equations combining creatinine and cystatin C, accuracy was the same across age, sex, diabetes status, albuminuria status, and body mass index categories." (PMID 41586348, 2026). "At the onset of diabetes, plasma levels of UA and cystatin C were significantly higher in individuals who later developed complications compared with those without complications." (PMID 41085706, 2026). "This score, comprised of information on depression, diabetes, cystatin C, FEV1, income, and educational attainment, performed better than the reference standard Fried frailty phenotype to identify outcome risks within age strata." (PMID 41426610, 2025). "Diabetes also increased plasma levels of cystatin-C by 40% in MRWT mice, indicating significant renal dysfunction." (PMID 41332229, 2025). "There were 8 cohorts with cystatin C available, including 453,628 individuals, and the mean age was 57 years, 53% were female, the mean BMI was 28 kg/m2, 6% had diabetes, the median ACR was 6 mg/g, and mean eGFRcr-cys was 94 mL/min/1.73 m2." (PMID 40914744, 2025). "This AGELESS Score includes depression, diabetes, cystatin C, FEV1, income, and educational attainment—all more strongly associated with frailty than chronologic age." (PMID 41426610, 2025). "Variables included demographics (age, sex, and marital status), comorbidities (hypertension, diabetes, and chronic diseases), lifestyle factors (smoking and alcohol use), biomeasures (grip strength, walking time, and cystatin C), and functional parameters." (PMID 40537082, 2025). "Data included demographics (age, sex), medical history (hypertension, diabetes), and lab markers (creatinine, cystatin C)." (PMID 40937180, 2025). "Univariate Cox regression indicated that age, AMI, diabetes mellitus, heart rate, serum creatinine, cystatin C, eGFR, fibrinogen, bSS, TyG index, LVEF, and the use of diuretics and insulin were significantly associated with the risk of MACEs (all p < 0.05)." (PMID 41295353, 2025). "Their logistic regression model incorporated variables such as the triglyceride-to-cystatin C ratio, systolic blood pressure, diabetes duration, diabetic retinopathy, HbA1c, and hemoglobin." (PMID 40529412, 2025). "Our data suggest using a combined creatinine- and cystatin C-based formula in European patients with diabetes mellitus to reduce these misclassifications." (PMID 39792299, 2025). "By studying three groups of obese patients with diabetes, metabolic syndrome, and simple obesity, they showed the highest cystatin C levels in patients with type 2 diabetes compared to the other groups." (PMID 39409098, 2024). "Another study of PAR-1 in DM nephropathy shows that after the establishment of diabetes, PAR-1-deficient animals showed decreased kidney damage, as seen by reduced proteinuria, plasma cystatin C levels, mesangial area expansion, and tubular atrophy." (PMID 38675414, 2024). "Recipients in the lowest creatinine-cystatin C ratio tertile were significantly older and had a higher prevalence of diabetes mellitus and hypertension." (PMID 38263396, 2024). "Among the initial cohort of 3800 patients, we included 2089 patients who had complete data about age, sex, cystatin C, creatinine, time to cardiovascular death, cardiovascular death, BMI, diabetes mellitus, current smoking, dyslipidemia, and hypertension." (PMID 38351263, 2024). "Other filtration markers such as serum cystatin C have therefore gained more interest, although serum cystatin C can also be affected by factors other than kidney function, such as inflammation and diabetes." (PMID 38213486, 2024).